IL4 (interleukin 4)
Diseases named in the same sentence as IL4 in open-access papers (continued):
Sharing a sentence is not in itself a finding about the gene and the disease.
Stroke (continued). "IL-4 also has anti-inflammatory effects and drives macrophages from a M1 proinflammatory phenotype to a M2 phenotype with homeostatic, repair and immune regulatory properties, explaining how IL-4 administration may improve recovery in a mouse stroke model." (PMID 34829993, 2021). "To investigate whether the CD200/CD200R signaling pathway is involved in regulating microglia activation and inflammatory factor release after stroke in rats, we assessed microglia activation using immunofluorescence and inflammatory factor (such as Il-1β, Il-6, Tnf-α, Il-4, and Cd206) release." (PMID 32473633, 2020). "This may have rescued functional deficits in IL-4 knockout mice suffering stroke." (PMID 32563258, 2020). "IL-4 post-treatment significantly reduced the g-ratio of the middle-sized (diameter = 400–800 nm) and large (diameter > 800 nm) axonal fibers, suggesting that IL-4 may maintain axonal myelination or promote axonal remyelination after stroke." (PMID 31226122, 2019). "Therefore, intranasal IL-4 delivery may represent a novel therapeutic strategy to improve white matter integrity in stroke and other brain injuries." (PMID 31226122, 2019). "Concurrently, stroke induces Th cell cytokine dysregulation, which is characterized by suppressed interferon-γ (IFN-γ) production and elevated interleukin-4 (IL-4) production by CD4+ T cells." (PMID 40618510, 2025). "Inflammatory response was determined by detecting levels of cytokines (interleukin-2 [IL-2], IL-4, IL-5, IL-8, IL-6, IL-10, IL-12p70, IL-17, tumor necrosis factor-α [TNF-α], interferon-γ [IFN-γ], IFN-α, and IL-1β) within 14 days after stroke onset." (PMID 38902691, 2024). "Distinct findings of higher plasma IL-4 and MIP-1β levels were observed in sCeAD patients compared to other stroke aetiologies." (PMID 38802464, 2024). "Genes involved in key signaling processes after stroke, including Il-10, Il-12, Hmgb1, Il-13, p38 MAPK, HIF1α, Stat3, and Il-4, were inhibited by NPD1 + RvD1." (PMID 37270727, 2023). "The pro-inflammatory (TNF-α, IL-1β, IL-6, IL-12 p40, and MIP-1α), and the anti-inflammatory (IL-4 and IL-10) mediators were examined by ELISA in IRF5 or IRF4 CKO aged mice plasma, 3 days after stroke." (PMID 35963621, 2022). "To further explore the potential mechanism of SNHG15 in stroke-induced immunosuppression, we investigated the response of SNHG15 to IL-4 or lipopolysaccharide (LPS) in sorted monocytes/macrophages by qRT-PCR." (PMID 34980176, 2022). "For trans-well co-cultures involving monocytes isolated from stroke blood, there was a significantly higher release of MCP-1 and IL-4, as compared to co-cultures using monocytes from healthy controls (p < 0.05)." (PMID 36277912, 2022). "Both IL-4 and TGF-β1 exerted a key role in promoting the protective activity of hyperforin in post-stroke angiogenesis and recovery." (PMID 34356309, 2021). "Of note, the AUCs for GDF-15, D-dimer, ADAMTS13, CCL2/MCP-1, IL-4, CC4b, IL-7, ferritin, SAA, CCL1/I-309 and IL-10 were ≥0.75 in indicating stroke amongst children with TBM." (PMID 33930055, 2021). "Additionally, human stroke patients have increased plasma levels of sST2, an inhibitory IL-33 receptor; while in mice, treatment with IL-33, a cytokine known to induce a shift toward M2 polarization, increased peripheral levels of IL-4 in the spleen and peri-infarct area." (PMID 34944064, 2021). "Notably, endogenous oligodendrocyte differentiation has been observed until as late as 3 mo after CNS injuries, and this prolonged effort may provide a sufficiently wide therapeutic window that allows delayed IL-4 treatment to restore white matter and encourage long-term stroke recovery." (PMID 31226122, 2019). "Third, IL-4 treatment increased the number of new, mature oligodendrocytes (APC+BrdU+) in the ischemic brain 35 d after stroke." (PMID 31226122, 2019).
Stroke (continued). "We observed in our model that IL-4 treatment robustly promoted microglia/macrophage polarization toward an anti-inflammatory phenotype (CD206+Iba1+) at 7 and 14 d after stroke." (PMID 31226122, 2019). "Several studies have shown that the percentages of cytotoxic T cells, natural killer (NK) cells, and B lymphocytes, and serum levels of TNF-α, IFN-γ, C-reactive protein (CRP), IL-4, IL-6, IL-10, and TGF-β are altered after stroke." (PMID 27682880, 2017). "Ischaemic stroke patients had elevated plasma levels of HGF and SDF-1α, and lower IL-4 levels, compared to spontaneous cervical artery dissection patients without stroke." (PMID 38802464, 2024). "Serum immunologic mediators IFN-γ, IL-4, and vitamin D may be useful biomarkers of AIS prognosis and may serve as therapeutic targets in improving stroke outcomes." (PMID 38870172, 2024). "We have found that the expression of the anti-inflammatory cytokine IL-4 is reduced in the peri-infarct cavity cortex of all stroke mice, which is not influenced by CCR5 knockout." (PMID 33532129, 2021). "In one study delivering recombinant IL-4 after stroke in IL-4 knockout mice, repeated measures were not accounted for and wild-type mice were not tested." (PMID 32563258, 2020). "Consistent with a reduced capacity to promote oligodendrogenesis, IL-4 failed to improve long-term sensorimotor or cognitive deficits after stroke in the absence of PPARγ." (PMID 31226122, 2019). "Frequency histograms revealed much greater reduction of axon diameters in the MCAO + vehicle group compared to the MCAO + IL-4 and sham groups, suggesting higher axonal degeneration in stroke mice without IL-4 treatment." (PMID 31226122, 2019). "Moreover, blockade of IL-4 and TGF-β abrogated the promoting role of hyperforin in post-stroke neurogenesis, angiogenesis and functional recovery." (PMID 31133816, 2019). "Astrocytic IL-6 was critical to the role of hyperforin in promoting the infiltration of T-helper (Th) type 2 cells to the ischemic hemisphere and Th2-derived cytokine IL-4, relative to Th1 and Th1-derived cytokine interferon-γ (IFN-γ), which decreased during stroke recovery." (PMID 31133816, 2019). "On the other hand, the level of IL‐4 transiently increased at 24 h and then significantly decreased at 3 and 10 days after stroke; no change in IL‐10 levels was observed at each specific time points." (PMID 29131464, 2018). "Also, 48 hr after stroke, BML‐111 induced a trend toward an increase in the levels of anti‐inflammatory cytokines IL‐10 and IL‐4 with BML‐111 treatment compared to the vehicle (both p = .1)." (PMID 28523230, 2017). "Neither microglia nor brain-recruited monocytes expressed detectable levels of the anti-inflammatory cytokines IL-4 and IL-10 after stroke (data not shown)." (PMID 26022493, 2015). "Finally, evaluation of the inflammatory Th1 (CD4+IFN-g+) and anti-inflammatory Th2 (CD4+IL4+) T-cells also did not reveal a change (count or percentage) in PNU-treated post-stroke mice." (PMID 40012683, 2025). "M2 microglia markers Il4, Arg1, and Fam19a3 were not changed by either hypertension or stroke." (PMID 38886874, 2024). "However, it must be noted that in a severe, permanent carotid artery occlusion model of stroke, simultaneous deletion of IL-13, IL-9, IL-4, and IL-5 did not worsen the neurological outcome." (PMID 36639371, 2023). "M2 phenotype is anti-inflammatory, which secretes anti-inflammatory cytokines such as interleukin-4 (IL-4), interleukin-10 (IL-10), transforming growth factor-β (TGF-β) and some neurotrophic factors, which facilitate brain function recovery and improve the prognosis of stroke." (PMID 35356292, 2022). "Importantly, depleting microglia induced a significant increase in the mRNA expression level of anti-inflammatory factors TGF-β1, Arg1, IL-10, IL-4, and Ym1 as well as a significant decline of pro-inflammatory factors TNF-α, iNOS, and IL-1β 3 days after stroke." (PMID 33757565, 2021).
Stroke (continued). "Hence, it indicates that the infiltration of Th2 cells into the ischemic hemisphere increased Th2-derived cytokine IL-4, increased Treg-derived IL-10 and TGF-β, as well as decreased Th1 and Th1-derived cytokine IFN-γ, which are all key events that promote angiogenesis during stroke recovery." (PMID 33967696, 2021). "Furthermore, mice receiving young microbiome possessed much higher levels of IL-4 and granulocyte-colony stimulating factor (G-CSF), while the elevation of levels of IL-6, tumor necrosis factor alpha (TNF-α), Eotaxin, and CCL5 were shown in the mice with aged microbiota after stroke." (PMID 33439913, 2021). "Furthermore, we observed a trend towards significantly higher IL‐10 and IL‐4 expression at 48 hr, indicating that BML‐111 may be maximally effective at reducing pro‐inflammatory cytokines and increasing anti‐inflammatory cytokines 48 hr after stroke." (PMID 28523230, 2017). "Silymarin raised cortical TNFα, IL4, IL10, IGF1, BDNF, and CX3CL1 levels in the HFD group with stroke, while the striatum did not present relevant differences." (PMID 39624169, 2024). "We initially screened 35 inflammatory mediators in 75 patients, and found that IL-4, IL-7, IL-9, GM-CSF and MIP-1α were significantly decreased in the severe stroke group, compared with control group (P < 0.05; data not shown)." (PMID 31164999, 2019). "Additional factors that may confer relative protection after experimental stroke in female mice are the increases in IL-10 secreting CD8+ T cells and an upregulation in IL-4 signaling, which are not seen in male mice." (PMID 35431903, 2022). "In addition, we observed trends (0.05<p-value≤0.09) in increased levels of GDNF, interleukin (IL)-7, MMP-9, lipocalin-2, IL-4, sP-selectin, and myoglobin, and lower levels of CC5a, in children with TBM-related stroke compared to TBM without stroke." (PMID 33930055, 2021).
melanoma (97 papers, 1996 to 2026). A malignant, usually aggressive tumor composed of atypical, neoplastic melanocytes. "The presence of IL-4 enhances tumor metastasis and the highly metastatic variant of B16 melanoma (B16F10) induces a distinct CD4 T cell subset capable of strong IL-4 production compared with T cells induced by the low metastatic variant (B16F1)." (PMID 39452870, 2024). "Along with Breslow thickness, infiltrating L-BCL2+, and serum IL-4, IL-6 and GM-CSF levels appear to be relevant risk factors for melanoma progression." (PMID 37046835, 2023). "According to this algorithm, a high Breslow thickness and serum IL‐4 levels in early‐stage melanoma patients are associated with a poor prognosis, whereas GM‐CSF and DCD levels decrease in patients in whom the disease outcome is poor." (PMID 32485045, 2020). "IL-4 is reportedly associated with cancer development via its suppression of inflammation and angiogenesis and directly inhibits the growth of human melanoma, renal cell carcinoma and gastric cancer cells." (PMID 26383107, 2015). "High metastatic variant of B16 melanoma (B16F10) induced a CD4+ T-cell population with strong IL-4 production compared to T cell induced by the low metastatic variant B16F1." (PMID 25208941, 2014). "In the development of melanoma, IL-4 emerges as a crucial cytokine for assessing metastatic risk." (PMID 40636453, 2025). "Models obtained using RapidMiner DTs show that the Breslow index, infiltrating L-BCL2+, and IL-4 levels are associated with a poor prognosis, whereas a decrease in GM-CSF serum levels directly identifies early-stage melanoma patients in whom the disease-free survival is less than 21.5 months." (PMID 37046835, 2023). "Elevated plasma levels of IL-4 were correlated with risk of acute myeloid leukemia, melanoma, head and neck squamous cell carcinoma, non-small-cell lung cancer, prostate, colon, breast, renal cell cancer, and were associated with poor prognosis in non-Hodgkin lymphoma." (PMID 25484626, 2014). "Drawing from cancer research data, particularly from melanoma studies, stimulation of IL-4 and RANTES appears to support the efficacy of therapies by modulating immune cell dynamics and inflammatory responses in the tumor microenvironment." (PMID 41596411, 2026). "In vitro experiments further indicated that IL-4 overexpression hampers melanoma cell proliferation through p21-mediated STAT6 pathway activation, leading to upregulated expression of apoptotic proteins." (PMID 40636453, 2025). "In line with our previous results, co-treatment of IL-4-stimulated BMDMs with Pam3 resulted in significantly larger tumors when mixed with B16 melanoma cells relative to IL-4 alone." (PMID 38585887, 2025). "This study primarily focused on one model of B16 melanoma in C57BL/6 mice where we were able to extrapolate that the IFN-I/IL-4 axis was correlated with outcomes in patients across multiple cancer types with TCGA data." (PMID 40367186, 2025). "When p21 was knocked down, melanoma cell growth suppression was reversed, accompanied by decreased IL-4 expression and reduced STAT6 activation." (PMID 40636453, 2025). "In a melanoma model, long-term antibiotic treatment disrupted intestinal flora, reduced IL-4 and TGF-β expression, and decreased IL-9-producing T cells in the tumor microenvironment." (PMID 40909266, 2025). "For instance, IL-4-secreting Th2 cells amplify metastatic behavior in melanoma models and drive macrophage polarization towards the M2 phenotype, which is recognized for its pro-tumorigenic properties." (PMID 40507238, 2025). "IL-4 significantly contributes to inhibiting melanoma progression, as evidenced by experiments involving IL-4-overexpressing transgenic mice compared to non-transgenic mice." (PMID 40636453, 2025). "Higher plasma levels of IL-2 and IL-4 have been found to significantly correlate with reduced pigmentation in melanoma patients, especially those with acral melanoma." (PMID 40636453, 2025).
melanoma (continued). "Here, we expanded the discoveries concerning the cytokines in melanoma based on some relevant results in our current study, where it was evident that the levels of IL-4, IL-13 and IL-35 in melanoma were all elevated following the silencing of EBI3." (PMID 39726752, 2024). "The relevant results have demonstrated that the concentrations of these specific cytokines including IL-35, IL-4 and IL-13 were all higher in melanoma cells with the presence of EBI3-specific small interfering RNA (p-value < 0.05)." (PMID 39726752, 2024). "In the human setting, a study reported enhanced circulating TGF-β+PD-L1+ B cells and TGF-β+:TNF-α+ B cell ratios and lower pro-inflammatory TNF-α+ B cells and IFN-γ+:IL-4+ B cell ratios as a feature of melanoma." (PMID 38533720, 2024). "In a similar phase II trial by the same group but instead in melanoma patients, only 1 patient responded to IL-4 therapy out of the 34 treated patients." (PMID 37455828, 2023). "Analysis of IFN-γ and IL-4 levels in the culture media of iNKT cells co-cultured for 4 days with melanoma cells in the presence of inhibitors revealed that 1MT and rofecoxib partially restored the release of both cytokines." (PMID 37444608, 2023). "In previous studies, IL-4 has been reported to be produced in various melanoma cells, including B16F10 cells." (PMID 33959512, 2021). "In a transgenic mouse model with overexpression of IL4, IL4/IL4Rα suppressed the development of melanoma through activation of the P21-mediated STAT6 pathway and inhibition of anti-apoptotic BCL2 expression." (PMID 33419470, 2021). "In B16F10 melanoma model, genetic or antibody-mediated IL-4 blockade promoted Vγ4 T cell-dependent antitumor functions." (PMID 34298791, 2021). "When extending findings with M(IL-4) polarized macrophages to patient melanoma-derived TAMs (which we defined as CD45 + CD3-CD11b + CD163 + cells), we observed again that these three β-glucans enhanced secretion of chemo-attractants." (PMID 32860527, 2021). "Our data also revealed the importance of IL‐10 and IL‐6 in predicting metastatic progression, albeit they provide a subleading and fluctuating contribution to melanoma outcome prediction compared to Breslow thickness and serum levels of IL‐4, GM‐CSF, and DCD." (PMID 32485045, 2020). "For example, it is reported that IL4 promoted tumor development via p21 mediated activation of STAT6 signaling pathways in IL4 downregulated melanoma models." (PMID 31540495, 2019). "IL-1α, IL-10, TGF-β, IL-8, and IL-4 mRNA were all upregulated during melanoma progression with a significant increase in metastatic compared to primary human melanomas suggesting transcriptional regulation." (PMID 30712866, 2019). "CD26neg T cells from melanoma patients secreted elevated IL-4, correlating with our previous finding that Th2 cells are prevalent in this culture." (PMID 29213079, 2017). "IL-4 transfection of cDNAs into mouse melanoma cells decreased the tumorigenicity of B16F10 melanoma cells by the activation of immune response." (PMID 26993600, 2016). "The melanoma cells were transfected with 100 nM siRNA of p21 for 24 hr, and then treated with IL-4 (50 ng/ml) for 24 hr." (PMID 26993600, 2016). "We tested a battery of cytokines, including IL-8, TNFα, MIP1, MCP1, IL-4, and IL-17a, in pretreatment (basal) serum samples of melanoma patients who responded to TIL treatment (n = 8) as compared with patients who failed to respond (n = 8)." (PMID 26688824, 2015). "Our microarray analysis also identified IL-4, Wnt, and Notch signaling pathway in the blood from melanoma patients compared with healthy control individuals." (PMID 21698244, 2011). "In response to autologous melanoma cell line, this clone is lytic and produced in decreasing order the following Th1 and Th2 cytokines: IL-13, IL-4, TNF-α, GM-CSF, IL-2, IFN-γ and IL-5." (PMID 20052413, 2010). "IL-4 enhances melanoma progression by interacting with preadipocytes." (PMID 40636453, 2025).